NLRP3 (NLR family pyrin domain containing 3)
Diseases named in the same sentence as NLRP3 in open-access papers (continued):
Sharing a sentence is not in itself a finding about the gene and the disease.
tumor (continued). "NLRP3 inflammasome has also been reported, in a head and neck squamous carcinoma (HNSC) mice model, to inhibit and delay tumor growth and reshape the anti-tumor response through a decrease in the number of immunosuppressive cells and an enhancement in the function of effector T cells." (PMID 33613533, 2020). "PYCARD, CASP-1, and NLRP3 protect against against tumorigenesis as shown in studies that demonstrated increased tumor growth in mice lacking NLRP3 inflammasome components." (PMID 33014808, 2020). "The O-GlcNAcylation of RACK1 may therefore modulate the melatonergic pathway in the tumour microenvironment via both YY1 and NLRP3." (PMID 33375613, 2020). "There was light and diffuse cytoplasmic staining for NLRP3 in tumor stromal cells, with little or no staining of surface epithelial cells." (PMID 31923221, 2020). "Despite the fact that necrotic cell death occurs during tumor progression releasing DAMPs, such as ATP, or uric acid, tumor growth was independent of NLRP3, suggesting either redundancy or the involvement of another PRR." (PMID 33042810, 2020). "Notably, HPK1 KD mice showed markedly increased pro-inflammatory pathways in response to priming with tumor antigens as shown by the enhanced related gene expression, e.g. S100A8, GZMB, NKp44, CXCL14, CX3CL1, CD1d2, KLRG1, CD11c, NLRP3 and MUC1." (PMID 30913212, 2019). "It was striking to find out that e-As4S4 significantly inhibited the NLRP3 expression, there was not appreciated positive staining of NLRP3 observed in most of the area in tumor tissues." (PMID 31106156, 2019). "Additionally, NLRP3 promoted the expansion of immune-suppressive macrophages in pancreatic ductal adenocarcinoma (PDAC), thus facilitating the generation of tumor-promoting T helper type 2 (Th2) cells and inhibiting the activation of cytotoxic CD8+ T cells." (PMID 31492049, 2019). "Nevertheless, NLRP3 and pro-IL-1β mRNA expression is not changed in CD11b+ Gr-1+ obtained from tumor-free (naive) or CT-26 tumor-bearing mice." (PMID 31217433, 2019). "However, in pancreatic ductal adenocarcinoma, studies have demonstrated that the inhibition or deletion of NLRP3, ASC, or caspase-1 decreases tumor growth and metastasis by reprogramming innate and adaptive immunity in the tumor microenvironment." (PMID 31242947, 2019). "MDSC (CD11b+ Gr-1+) are cells that highly express NLRP3 and pro-IL-1β mRNA, compared to their counterpart Gr-1 negative cells purified from spleen of CT-26 tumor-bearing mice." (PMID 31217433, 2019). "And 5-FU treatment could further increase the expression and activation of NLRP3 inflammasome in OSCC cells, which in turn attenuated its anti-tumor effect." (PMID 29716544, 2018). "Additionally, chemotherapy triggers cathepsin B release in myeloid-derived suppressor cells, activating the NLRP3 inflammasome leading to MDSC-derived IL-1β and angiogenesis and promoting tumor growth and metastasis." (PMID 30631327, 2018). "In a model of chemically-induced carcinogenesis, mice lacking NLRP3 showed low tumor burden and suppression of metastasis." (PMID 30631327, 2018). "On cellular level, DC that lacked inflammasome activity when incubated with dying tumor cells that released ATP as a NLRP3 inflammasome inducer were no efficient CTL inducers." (PMID 30042333, 2018). "Others have reported that NLRP1 can activate caspase 2 and − 9 in neoplasm cells resulting in tumorigenesis, but NLRP3 did not appear to be tumorigenic." (PMID 30447690, 2018). "Maybe just like NLRP3, we speculate that NLRP1 becomes activated in tumor microenvironment by inflammatory factor, endogenous ATP, cell damage, HMGB1, or potassium efflux." (PMID 29214170, 2017).
tumor (continued). "Another study found that tumor-derived autophagosomes, which is also known as defective ribosomal products in blebs (Dribbles), can induce the maturation of DCs and the secretion of proinflammatory cytokines in TLR and NLRP3 inflammasome-dependent manner." (PMID 28360909, 2017). "However, several studies have shown that EBV infection can induce the NLRP3 inflammasome to produce IL-1β and IL-18, leading to the growth and activation of anti-apoptosis mechanisms of EBV-infected tumor cells." (PMID 28732079, 2017). "We identified 4.1-fold increase in Nlrc4 mRNA but not Nlrp3 expression in tumours from DIO mice compared with those from ND mice." (PMID 27708283, 2016). "Although the role of inflammasomes in anticancer activity is not fully understood, it is suggested that the mice lacking NLRP3 have a low tumor burden and suppression of tumor metastasis." (PMID 27429614, 2016). "To rule out a potential difference in NLRP3 expression in lung TAMs, we performed a flow cytometry analysis on digested lungs obtained from tumor-bearing mice." (PMID 27528423, 2016). "Even through this study focused on NLRP3 inflammasome, it does not exclude the possibility that other inflammasomes are involved in tumor growth and metastasis." (PMID 27786298, 2016). "MM tumor cells/tissues showed decreased levels of inflammasome components like NLRP3 and caspase-1 as compared to human mesothelial cells or normal tissue counterpart of tumor." (PMID 26689911, 2015). "This study showed the relevance of interactions between TLR4, NLRP3 and NOD1 in LM-induced DC maturation and anti-tumor responses, which help us understand the immune regulatory mechanisms involved in LM vaccine-related tumor immunotherapy." (PMID 25826093, 2015). "Another study found that extracts from an anti-tumorigenic mushroom functioned by activating the same P2RX7/NLRP3 pathway in macrophages, but did not draw a direct link to altered tumor kinetics." (PMID 24795727, 2014). "Although most of these chronic models did not evaluate potential alterations in anti-tumor adaptive immunity, one study showed that in the absence of NLRP3 and caspase-1, reduced IL-18 in a colorectal tumor model led to diminished IFN-γ levels in the colon." (PMID 24409181, 2013). "None of the patients whose tumours showed upregulation of AIM2 or NLRP3 inflammasomes had local recurrence within 5 years after treatment." (PMID 23065753, 2012). "We found that 25 out of the 33 tested inflammasome-related genes were detectable by quantitative RT-PCR, and 8 of them (CIITA, NLRC4, NLRP3, NLRP7, AIM2, RIG-I, ASC and IL-1β) were overexpressed (fold change, >2) in NPC tumour samples, compared to adjacent normal samples." (PMID 23065753, 2012). "Therefore, this study investigated the protein expression of NLRP3, ASC, caspase‐1, IL‐1B, IL‐18, IL‐1RA, and IL‐18BP on tumor cells by utilizing multiplexed immunohistochemistry on PDAC and IPMN samples, examining their association with pathological features and prognoses." (PMID 39969214, 2025). "Extracellular ATP activates the P2X7 receptor on Mφ surface, inducing NLRP3 inflammasome-dependent IL - 1β release and upregulating the expression of MHC-II molecules and costimulatory molecules CD80/CD86, thereby promoting the cross-presentation of tumor antigens to CD4+ T cells." (PMID 41019083, 2025). "Similarly, after NLRP3 inflammasome activity was inhibited, IL-1β secretion decreased, attenuating inflammatory cascades in the TME, which helps reduce pro-tumorigenic inflammation in the tumor microenvironment." (PMID 41415576, 2025). "Its coordinated expression with NLRP3, particularly in HER2+ tumors, points to a potential ALKBH7–NLRP3 co-expression that could shape the tumor microenvironment dynamics and serve as a prognostic biomarker or therapeutic target, especially in aggressive subtypes such as HER2+ and TNBC." (PMID 41373809, 2025).
tumor (continued). "In neutrophils, eosinophils, MCs, and macrophages, KMF exerts anti-inflammatory or anti-tumor effects by inhibiting inflammatory signaling pathways, reducing cell infiltration, or regulating polarization states, with mechanisms involving NF-κB, MAPK, and NLRP3 inflammasome." (PMID 40918131, 2025). "Further mechanistic insights reveal that the NLRP3 inflammasome may also contribute to chemoresistance; genetic ablation of NLRP3 enhances the antitumor efficacy of 5-fluorouracil (5-FU) in OSCC models, delaying tumor onset and reducing tumor burden." (PMID 41560727, 2025). "MT also repressed GC cell proliferation (Ki67 index: 34.98% in SGC7901 xenograft mouse models without MT vs. 12.02% in those with MT) and attenuated NLRP3 activation (NLRP3 area: 18.32% in SGC7901 xenograft mouse models without MT vs. 11.07% in those with MT) in SGC7901 mouse tumour models." (PMID 38616702, 2024). "In this regard, LPS and ATP were used for canonical NLRP3 inflammasome activation and pyroptosis induction, while MCC950 was used for specific inhibition of NLRP3 and IL-1β release, after which PTX was added to suppress the proliferation of tumor cells and programmed cell death initiation." (PMID 39433537, 2024). "MCC950 also repressed GC cell proliferation (Ki67 index: 34.60% in SGC7901 xenograft mouse models without MCC950 vs. 11.57% in those with MCC950) and NLRP3 activation (NLRP3 area: 17.47% in SGC7901 xenograft mouse models without MCC950 vs. 10.87% in those with MCC950) in SGC7901 mouse tumour models." (PMID 38616702, 2024). "Moreover, tumor hepatocytes display upregulated levels of long noncoding RNA SNHG7, which induces the miR34a/SIRT1 pathway, strictly connected to the pyroptosis program via the canonical NLRP3 inflammasome pathway." (PMID 37891577, 2023). "Interestingly, in murine invasive breast cancer models, the absence of a functional NLRP3 inhibited tumor growth, and NK cell depletion abolished the anti-tumoral effect independently of IL-1 β and IL-18 effector mechanisms." (PMID 37715239, 2023). "According to one study, NLRP3 expression may influence the composition ratio of B, T cells, and macrophages in the immunological microenvironment of SKCM tumor tissue, therefore indirectly modulating immune monitoring and influencing tumor progression." (PMID 37715239, 2023). "Moreover, NLRP3 inflammasome activation can also promote angiogenesis by inducing the expression of vascular endothelial growth factor (VEGF) and other angiogenic factors in tumor cells and endothelial cells." (PMID 37715239, 2023). "The in vivo experiments indicated that butyrate could reverse the aggravation of intestinal inflammation and the accelerated tumor growth induced by HFD-FMT, and the NLRP3/Caspase-1 pathway in the colon activated by HFD-FMT was also significantly inhibited by butyrate." (PMID 37781523, 2023). "Besides IL-1β, IL-18 secreted by tumor cells through NLRP3 is positively correlated with PD-L1 expression and negatively correlated with cytotoxic T cells." (PMID 36932407, 2023). "However, the tumor‐promoting role and specific mechanism of NLRP3 in the HCC microenvironment have not yet been fully elucidated." (PMID 38116060, 2023). "In addition, treatment with exogenous butyrate reversed the M1 polarization of proinflammatory macrophages, aggravation of intestinal inflammation, and accelerated tumor growth induced by HFD; the NLRP3/Caspase-1 pathway activated by HFD in the colon was also significantly inhibited." (PMID 37781523, 2023). "Given that the hazard ratio of NLRP3 in the prognostic model was 0.68 (P = 0.039), we additionally conducted IHC analyses of NLRP3 staining in samples from 176 patients with HNSCC, the results demonstrated that the NLRP3 was significantly correlated with tumor size (P = 0.023)." (PMID 35123464, 2022).
tumor (continued). "Our scRNA-seq dataset further showed that NLRP3+ and INHBA+ macrophages also expressed several well-characterized immune-suppressive tolerogenic molecules, suggesting efferocytosis can activate a unique heterogeneous complex signature in tumor-infiltrating mononuclear phagocytes." (PMID 36439171, 2022). "However, because of a lack of studies of the mechanisms through which NLRP1 and NLRP3 regulate tumor immune cell infiltration in GC, more experimental studies are needed." (PMID 36541912, 2022). "For instance, BGL was found to inhibit the release of IL-1β upon NLRP3 inflammasome activation, and BGL can also promote the maturation of tumor-educated dendritic cells (TEDCs), which subsequently enhances antitumor immune responses and inhibits tumor progression." (PMID 36142202, 2022). "Therefore, the MEG3/NLRP3/caspase-1/GSDMD pathway may be one of the important mechanisms for DDP to induce pyroptosis and exert anti-tumor effects in TNBC." (PMID 34326697, 2021). "However, NLRP3 knockout mice had no change in tumor formation or tumor frequency compared to wild-type mice." (PMID 34571825, 2021). "We observed that IL-4 promotes a positive feedback loop by i) promoting NLRP3 nuclear localization, ii) boosting TOX expression and TOX+ cell proliferation, which upregulates IL-4, and iii) favoring a dominance of Th2 responses in advanced stages of the disease (tumor)." (PMID 34220814, 2021). "Additionally, we observed that the combination of NLRP3 inhibition and anti–PD-1 treatment significantly increased the antitumor efficacy of the monotherapy by limiting MDSC-mediated T cell suppression and tumor progression." (PMID 33649199, 2021). "With reduced IL‐1β activity, there is less tumor-derived IL-1β and IL-6 activity on bone marrow cells and ultimately decreased STAT3 activity in this cell population, supporting our previous findings that tumor-NLRP3 activity induces IL-1β and IL-6 in the bone marrow." (PMID 34531850, 2021). "Overall, these observations indicate that the reduction in tumor growth following NLRP3 inhibition is not mediated by a reduction in tumor cell proliferation or by a direct effect on CD8+ T cells, but rather by the reduction MDSCs expansion and their immunosuppressive activities." (PMID 33649199, 2021). "Our results suggest that doxycycline has an inhibiting effect on LPS priming of the inflammasome, and that it can attenuate the production of pro-CASP1 and NLRP3 RNA and NLRP3 protein assembly irrespective of the level of IL-1β production and secretion in these tumor cells." (PMID 34577552, 2021). "Furthermore, tumor-derived autophagosomes can strongly activate innate immune responses and NLRP3 inflammasomes in the absence of LPS priming and are, therefore, being tested as therapeutic cancer vaccines." (PMID 32703253, 2020). "A possible explanation for the lack of increased NLRP3 expression, despite elevated caspase-1, IL1β and IL18, is that only specific locations have cells with activated NLRP3 (i.e., a cluster of invading immune cells at the tumor/tissue interface) and tissue was from regions without altered NLRP3." (PMID 31923221, 2020). "However, recently it was demonstrated that NLRP3 activation is not an exclusive feature of immune cells, and it was also detected in tumor cells, while its role in tumorigenesis remains controversial." (PMID 33613529, 2020). "Notably, the activation of NLRP3/caspase-1 signaling induces apoptosis rather than pyroptosis in tumor cells lacking GSDMD." (PMID 31501419, 2019). "However, in agreement with the experiments performed in Nlrp3−/− mice, FACS analysis of immune cell infiltration into Met-1 tumours revealed that genetic depletion of inflammasome signalling in CAFs resulted in attenuated recruitment of CD11b+Gr1+ myeloid cells." (PMID 31558756, 2019).
tumor (continued). "ATP released by dying tumor cells functions as a “find me” signal attracting myeloid cells, including DC, to the tumor bed via binding to the purinergic receptor, P2X7, on DC and stimulating NLRP3 inflammasome activation and the proteolytic maturation of IL-1β." (PMID 29462947, 2018). "Importantly, these necrotic areas showed enhanced expression of both caspase-11 and NLRP3, demonstrating that tumor cell death occurred through caspase-11-mediated non-canonical inflammasome activation." (PMID 30526845, 2018). "The OT1-mediated killing of target tumour cells in vivo induced IL-1β production through antigen presentation and NLRP3 inflammasome, indicating that the OVA tumour antigen was presented by APCs to activate OT1 T cells, and the CTLs then activated NLRP3 inflammasome in APCs." (PMID 28537251, 2017). "To determine whether the NLRP3 inflammasome activated by tumour antigen-specific CTLs contributes to their mediated antitumour immunity, we utilized a similar strategy to analyse the ability of OT1-mediated antigen-specific killing of target tumour cells." (PMID 28537251, 2017). "In addition, our western blot results showed that NLRP3, Caspase-1, IL-18 and IL-1β were highly expressed in the Tgfbr1/Pten 2cKO mice SCCHN tumor lysates compared with control wild type tongues, and the expression of BMI1, ALDH1 and CD44 were consistent with NLRP3 inflammasome." (PMID 28865486, 2017). "In particular, the activation of NLRP3 inflammasome via TLR4 signalling led to IL-1β release after caspase-1 activation, whereas, the activation of caspase-11 was important for both IL-1α release and NLRP3-dependent IL-1β release in the lung of tumor-bearing mice." (PMID 27528423, 2016). "First, quantitative thresholds of pyroptosis component expression, such as caspase-3/8, GSDME, and NLRP3 may determine whether the net effect is anti- or pro-tumor, suggesting that fine-tuned modulation rather than binary activation/inhibition could optimize therapeutic impact." (PMID 41291696, 2025). "However, a comparative study assessing NLRP3 (NOD-like receptor protein 3), caspase-1, IL-1β, and IL-18 mRNA and protein expression in hen and human OvCa found increased protein expression of caspase-1, IL-1β, and IL-18 in surface epithelium, tumor cells, and immune cells." (PMID 40718836, 2025). "However, in order to understand the tumor microenvironment better with the ultimate aim of introducing a new, safe, and efficacious clinical chemotherapeutic drug, the regulation of PDAC tumor cells microenvironment by the NLRP3 inflammasome needs to be further studied in vivo and in human cells." (PMID 38018872, 2023). "Moreover, tumor PD-L1, PD-1, or PD-L1 im-munotherapy blockade activated NLRP3 leading to resistance in BC as reviewed by our research group, highlighting the fact that CALR/NLRP3 and PD-L1/sPD-L1 might provoke an immunosuppressive/resistance loop in BC." (PMID 37762557, 2023). "In contrast, cluster of differentiation 38 (CD38) has been demonstrated to act as a tumor suppressor gene in HNSCC, triggering pyroptotic cell death by activating NLRP3 and caspase-1; thus, by inhibiting CD38 expression, HNSCC cells might be able to escape NLRP3 inflammasome-mediated pyroptosis." (PMID 34064909, 2021). "In addition, it is not understood whether there are tumor-specific pathways that uniquely modulate NLRP3 function relative to the regulatory networks that have been shown to control NLRP3 activity in myeloid cells." (PMID 34638239, 2021). "Interestingly it has also been demonstrated that, in murine invasive breast cancer models, the absence of a functional NLRP3 impaired tumor growth, and NK cell depletion abolished the anti-tumoral effect independently from effector mechanisms of IL-1β and IL-18." (PMID 33840390, 2021).